XIAP (X-linked inhibitor of apoptosis)
Diseases named in the same sentence as XIAP in open-access papers (continued):
Sharing a sentence is not in itself a finding about the gene and the disease.
lymph node metastasis (5 papers, 2012 to 2023). "In multivariate analysis, lymph node metastasis, alcohol consumption and XIAP expression (pre-chemotherapy) were independent risk factors for patients' prognosis." (PMID 22403616, 2012). "Multivariate analysis demonstrated that only alcohol consumption, lymph node metastasis and XIAP level were independently associated with the prognosis of advanced HNSCC patients." (PMID 22403616, 2012). "Similarly for patients with lymph node metastasis we identified four proteins, namely IL1α, XIAP, STX2, and SHKBP1, whereas for patients with liver metastasis we identified IGF1, IL1α, IGFBP2, MAML3, and SHKBP1 as significant." (PMID 24282616, 2013). "The hypothesis that this XIAP stimulated immune cell infiltrate is anti-tumoral for patients’ outcome in PDAC but detrimental in other entities and the role of XIAP in lymph node metastasis should be evaluated in further sophisticated mechanistic studies in animal as well as in vitro models." (PMID 36472768, 2023).
oral cancer (5 papers, 2014 to 2025). "Immunoblotting analysis for the expression of active caspase-3 and X-linked inhibitor of apoptosis protein indicated that Danshen extract-induced apoptosis in human oral cancer SAS cells was mediated through the caspase pathway." (PMID 29284481, 2017). "Overall, these findings demonstrate that hellebrigenin initiates oral cancer cell apoptosis by downregulating XIAP expression." (PMID 38044583, 2024). "Our observations revealed that Alisol A remarkably diminished the levels of cIAP1 and XIAP, suggesting that inhibition of cIAP1 and XIAP may be involved in the Alisol A-provoked apoptosis of oral cancer cells." (PMID 41179293, 2025). "Because XIAP has been demonstrated to be a potential target for anti-cancer therapy, the effect of NSC745885 in the suppression of this critical regulator of apoptosis may demonstrate a therapeutic potential for treating oral cancer." (PMID 25127132, 2014).
ovarian tumor (5 papers, 2013 to 2022). "Other researchers have confirmed this finding, showing that the acquisition of cisplatin resistance is associated with the ability of cisplatin-treated ovarian tumor cells to upregulate XIAP expression." (PMID 23817665, 2013). "In vivo, XIAP inhibition in ovarian tumor models inhibits tumor growth and increases the survival rate in mice." (PMID 30552344, 2018). "In the present study, β-elemene suppressed XIAP expression and blocked cisplatin-induced XIAP upregulation in resistant ovarian tumor cells." (PMID 23817665, 2013). "In the current study, β-elemene promoted cisplatin cytotoxicity and apoptosis by blocking cisplatin-induced increases in the levels of ERCC-1 and XIAP in resistant ovarian tumor cells." (PMID 23817665, 2013). "Limitations of this study include the genetic heterogeneity of the ovarian tumour cell lines and human samples used, and the fact that the correlation between XIAP and BRCA status could affect the survival of patients after treatment with IAPs inhibitors." (PMID 35501389, 2022). "Moreover, miR‐149 inhibited growth and induced sensitivity of ovarian tumour cell to cisplatin through targeting XIAP." (PMID 34378327, 2021). "Furthermore, our analyses showed that these two inhibitors synergistically inhibited the survival of ovarian tumor cells via activation of the Caspase 8/XIAP-dependent pathway." (PMID 28134933, 2017). "Several studies have reported that targeting XIAP, and more generally all IAP proteins, enhanced cell death in vitro and sensitized platinum-resistant ovarian tumor cells." (PMID 30552344, 2018).
renal carcinoma (5 papers, 2009 to 2021). A carcinoma arising from the epithelium of the renal parenchyma or the renal pelvis. "miRNA-212 suppresses the X-linked inhibitor of apoptosis protein that constrains renal cancer invasion and proliferation, raising questions about a possible role in TSC-associated lymphangioleiomyomatosis." (PMID 34262466, 2021). "To determine whether Bcl-2 and XIAP downregulation was a cause or a consequence of caspase activation and apoptosis, we treated A498 renal cancer cells with DMSO, AR-A014418, DEVD-CHO (reversible tetrapeptide inhibitor of caspase-3 and caspase-7) or a combination of AR-A014418 and DEVD-CHO." (PMID 19920820, 2009). "We observed that inhibition of GSK-3 results in decreased expression of NF-κB target genes Bcl-2 and XIAP and a subsequent increase in renal cancer cell apoptosis." (PMID 19920820, 2009). "Increased expression of Bcl-2 and XIAP anti-apoptotic molecules, NF-κB target genes, has an important function in renal cancer cell survival and chemoresistance." (PMID 19920820, 2009). "Taken together, our results suggest that inhibition of GSK-3 suppresses the expression of NF-κB target genes Bcl-2 and XIAP, resulting in decreased survival of renal cancer cells." (PMID 19920820, 2009). "Increased expression of Bcl-2 and XIAP anti-apoptotic molecules, NF-κB target genes, has an important function in renal cancer cell survival and chemoresistance and resistance to immunotherapy." (PMID 19920820, 2009). "Increased expression of Bcl-2 and XIAP anti-apoptotic molecules, NF-κB target genes has an important function in renal cancer cell survival." (PMID 19920820, 2009). "Using real-time PCR, we found that inhibition of GSK-3 resulted in a marked reduction in the expression of NF-κB target genes Bcl-2 and XIAP, suggesting a downregulation of NF-κB transcriptional activity in renal cancer cells." (PMID 19920820, 2009). "Here, we found that inhibition of GSK-3 suppresses NF-κB-mediated expression of Bcl-2 and XIAP leading to a decreased survival of renal cancer cells." (PMID 19920820, 2009). "In this study, we show that inhibition of GSK-3 suppresses NF-κB-mediated expression of Bcl-2 and XIAP leading to a decreased survival of renal cancer cells." (PMID 19920820, 2009). "Our finding of nuclear accumulation of GSK-3β suggests the possibility that GSK-3β could positively regulate NF-κB-mediated transcriptional activation of Bcl-2 and XIAP in the nucleus of renal cancer cells." (PMID 19920820, 2009). "As GSK-3β has a positive role in expression of certain NF-κB-regulated genes, we investigated whether inhibition of GSK-3 affects NF-κB-mediated expression of Bcl-2 and XIAP in renal cancer cells." (PMID 19920820, 2009). "Human renal cancer cells (Caki cells) overexpressing Par-4 were sensitized to apoptosis by inductor TRAIL and drugs that induce endoplasmic reticulum stress (i.e., thapsigargin, tunicamycin and etoposide) associated with decreased levels of XIAP protein and caspase activation." (PMID 23760770, 2013). "A significant correlation was found between XIAP expression levels (ratio to actin, GAPDH) and the sensitivity to A4 (IC50, μM) in breast, ovary and kidney carcinomas." (PMID 32587235, 2020). "Using western immunoblotting, we found that inhibition of GSK-3 resulted in a significant decrease in the expression of anti-apoptotic proteins Bcl-2 and XIAP in ACHN and Caki1 renal cancer cells." (PMID 19920820, 2009). "BIX also generated intracellular ROS in human renal carcinoma Caki cells, but ROS scavengers were not affected by combined treatment with BIX and TRAIL and BIX-mediated modulation of XIAP, survivin, and DR5 expression." (PMID 29531826, 2018).
retinal degeneration (5 papers, 2007 to 2020). Degeneration of the retina. "In models of retinal degeneration, the increase of XIAP levels was previously shown to have a protective role." (PMID 31837604, 2020). "Experimental gene delivery studies with XIAP suggest some degree of structural and functional rescue to PRs in both acute and chronic rodent models of retinal degeneration." (PMID 24367709, 2013). "In addition, we have previously shown that XIAP over-expression can protect photoreceptors both structurally and functionally in a chemotoxic animal model of retinal degeneration." (PMID 17375200, 2007). "We hypothesized that AAV mediated delivery of XIAP should provide neuroprotection in these progressive retinal degenerations given its efficacy in acute insult." (PMID 17375200, 2007). "It is important to note that the XIAP treatment does not represent an all-encompassing gene therapy strategy for retinal degeneration." (PMID 17375200, 2007).
adenoma (4 papers, 2005 to 2023). A neoplasm arising from the epithelium. "The p16 protein has been associated with the X‐linked inhibitor of apoptosis protein (XIAP) in both benign and malignant neoplasm such as adenoma, and bronchiolo‐alveolar carcinoma of the lung." (PMID 32945604, 2020). "Although XIAP levels were slightly higher in the parental adenoma cell line AA/C1 than in AA/C1/SB/10, the other cell lines had similar expression levels of XIAP." (PMID 15685228, 2005). "The mRNA expression of livin, its isoforms α and β, XIAP, CASP3 and DIABLO was evaluated by qRT-PCR in 82 fresh-frozen adrenal tissues (34 ACC, 25 adenomas = ACA, 23 normal adrenal glands = NAG)." (PMID 28030838, 2017).
anaplastic thyroid cancer (4 papers, 2016 to 2024). "It should be noted that XIAP is highly expressed in anaplastic thyroid carcinoma and affects cancer cell activities." (PMID 39051062, 2024).
breast invasive ductal carcinoma (4 papers, 2011 to 2017). "It has also been reported that XIAP nuclear labeling was a sign of unfavorable prognosis in breast invasive ductal carcinoma." (PMID 25216527, 2014). "Disturbed balance of expression between XIAP and Smac probably contributed to carcinogenesis and XIAP-N was a new independent prognostic biomarker of breast invasive ductal carcinoma." (PMID 21645409, 2011). "Disturbed balance of expression between XIAP and Smac probably contributed to carcinogenesis and XIAP positive nuclear labeling was a sign of unfavourable prognosis in breast invasive ductal carcinoma." (PMID 21645409, 2011). "However, expression status and biologic or prognostic significance of XIAP/Smac in breast invasive ductal carcinoma (IDC) were not clear." (PMID 21645409, 2011).
diabetes retinopathy (4 papers, 2019 to 2021). "For instance, circ_0005015 elevates the expression of MMP-2, XIAP, and STAT3 thereby promoting the development of diabetes retinopathy via acting as a molecular sponge of miR-519d-3p." (PMID 32600379, 2020).
gastric adenocarcinoma (4 papers, 2009 to 2016). "In AFP producing gastric adenocarcinoma group, the risk scores were calculated based on 3 independent factors including XIAP, IGF-Irβ and TNM stage, as well as their corresponding regression coefficients." (PMID 27057629, 2016). "In AFP producing gastric adenocarcinoma group, poor RSF and OS were associated with high levels of expression of XIAP (log rank, p=0.016 and p=0.013, respectively), IGF-Irβ (p=0.024 and p=0.028) and Autotaxin (p=0.034 and p=0.011)." (PMID 27057629, 2016). "Previous studies demonstrated that XIAP is up-regulated in many gastric adenocarcinoma cells and XIAP inhibitors can increase apoptosis and enhance sensitivity of gastric adenocarcinoma cell lines to chemotherapy." (PMID 27057629, 2016). "A risk model based on the XIAP and IGF-Irβ expression levels can separate AFP producing gastric adenocarcinoma patients into 2 subgroups and each subgroup had a distinct set of signaling pathways involved." (PMID 27057629, 2016). "Here, the apoptotic events are characterized by the activation of anti-apoptotic proteins, for example decreased BNIP3 and elevated XIAP in human gastric adenocarcinoma, which interact with apoptotic and/or anti-apoptotic molecules in human gastric adenocarcinoma." (PMID 24527069, 2014). "However, anti-apoptosis markers, particularly XIAP, were markedly increased in low grade differentiated gastric adenocarcinoma cells." (PMID 24527069, 2014). "That the finely tuned balance between XIAP and its antagonists is critical in determining the clinical outcome in cancer patients was demonstrated in an analysis of 187 gastric adenocarcinomas in which the expression levels of XIAP and its antagonising factors including SMAC and XAF1 were examined." (PMID 20485285, 2010). "Therefore, XIAP is considered as a potential target for gastric adenocarcinoma therapy." (PMID 27057629, 2016). "Therefore, a high level expression of XIAP in gastric adenocarcinoma cells, which reduces cancer cell apoptosis, could be a reason for the poor prognosis in the AFP-producing gastric adenocarcinoma patients." (PMID 27057629, 2016). "In univariate analyses of AFP-producing gastric adenocarcinoma group, higher TNM stage and increased expression of XIAP, IGF-Irβ and Autotaxin were found to be correlated with poor RFS and OS." (PMID 27057629, 2016). "In addition, the high level expression of XIAP and IGF-Irβ in gastric adenocarcinoma tissues was independent factors for poor prognosis in AFP producing gastric adenocarcinoma patients." (PMID 27057629, 2016). "In contrast, in AFP non-producing gastric adenocarcinoma group, none of 11 differentially expressed proteins, XIAP IGF-Irβ and Autotaxin included, were demonstrated association with RSF and OS." (PMID 27057629, 2016). "Moreover, in gastric adenocarcinomas, the expression ratio between XIAP and XAF1 increases and the expression balance of XIAP and XAF1 is an independent prognostic factor." (PMID 19397802, 2009). "More importantly, our study showed that the high level expression of XIAP and IGF-Irβ were independent prognostic factors and correlated with poor survival in AFP producing gastric adenocarcinoma patients but not in the AFP non-producing patients." (PMID 27057629, 2016). "However, to our knowledge, dysregulation of cyclin D1, RANKL, LSD1, Autotaxin, Calpain2, XIAP, IGF-Irβ, ASC-R and BID in AFP producing gastric adenocarcinoma has not been reported before." (PMID 27057629, 2016).
Griscelli syndrome type 2 (4 papers, 2018 to 2025). Griscelli syndrome type 2 (GS2) is a rare, inherited condition that affects the skin, hair, and immune system. "In 13 out of the 24 (52%) a genetic diagnosis was achieved: PRF1 n = 4 (FHL2), STX11 n = 2 (FHL4), and STXBP2 n = 4 (FHL5), RAB27A n = 2 (Griscelli syndrome type 2), BIRC4 n = 1 (XIAP)." (PMID 30697212, 2018).
ischemia (4 papers, 2013 to 2021). A hypoperfusion of the BLOOD through an organ or tissue caused by a PATHOLOGIC CONSTRICTION or obstruction of its BLOOD VESSELS, or an absence of BLOOD CIRCULATION. "There has been a study revealing that XIAP is declined in rats suffering from cerebral ischaemia reperfusion injury, and a previous study has clarified that XIAP protein levels were decreased in both sexes after stroke." (PMID 32790238, 2020). "The upregulation of XIAP suppresses ischemic damage in the hippocampus and also recovers neurologic function of adult rat after global ischemia." (PMID 31660045, 2019). "Smac, a mitochondria protein released into the cytosol in response to some of the apoptotic stimuli, including ischemia, was found to promote caspase activation by binding and neutralizing the IAPs, including XIAP, IAP-1, and IAP-2." (PMID 23308180, 2013). "In addition, processed HTRA2 released into the cytosol after ischemia contributes to neuronal injury via inhibition of XIAP." (PMID 34708890, 2021).
liver fibrosis (4 papers, 2022 to 2025). "Furthermore, XIAP has been implicated in the regulation of inflammation through its interaction with NF-κB and other signaling molecules, suggesting a possible role in the inflammatory response observed in liver fibrosis." (PMID 39629085, 2024). "The potential involvement of XIAP in macrophage polarization and function could have significant implications for the progression of liver fibrosis." (PMID 39629085, 2024). "In addition, we demonstrate that XIAP-mediated downregulation of IFT88 in HSCs exacerbates liver fibrosis." (PMID 38351372, 2024). "Given that multiple anti-XIAP drugs have been developed for the treatment of various diseases, further studies are warranted to examine their therapeutic potential in liver fibrosis." (PMID 38351372, 2024). "In CPF group, apoptotic gene Bax and liver fibrosis gene TIMP were increased, while anti-apoptotic gene XIAP was decreased." (PMID 36152060, 2022). "Blocking XIAP-mediated IFT88 degradation prevents TGF-β-induced HSC activation and liver fibrosis." (PMID 40076734, 2025). "Blocking XIAP-mediated IFT88 degradation ablates TGF-β-induced HSC activation and liver fibrosis." (PMID 38351372, 2024).
mesothelioma (4 papers, 2010 to 2018). A usually malignant and aggressive neoplasm of the mesothelium which is often associated with exposure to asbestos. "XIAP is known as a protein that inhibits the apoptotic pathway by inhibiting caspases, and its overexpression has been reported in human mesothelioma." (PMID 29719620, 2018). "Various therapies are under development targeting IAPs and in particular XIAP and survivin in a number of malignancies and we wanted to investigate in detail the potential of such therapies in mesothelioma using a panel of cell lines." (PMID 23229133, 2013). "Since immunoblotting studies indicated differential expression of both XIAP and survivin protein in mesothelioma cell lines we further investigated the role of these proteins in resistance to cisplatin using RNAi mediated knockdown." (PMID 23229133, 2013). "In contrast, protein expression of both XIAP and survivin was upregulated in all mesothelioma cells, consistent with post-translational regulation." (PMID 23229133, 2013). "A recent study has suggested that LBH589 enhances TRAIL-induced apoptosis through downregulation of XIAP in mesothelioma cells." (PMID 20442774, 2010). "Because CTGF has been reported to enhance TGF-β signals, CTGF inhibition may lead to downregulation of XIAP in mesothelioma by altering these pathways." (PMID 29719620, 2018). "Our data indicate that inhibition of caspase activation by XIAP was not likely to be important in the resistance of mesothelioma cell lines to cisplatin." (PMID 23229133, 2013).
pancreatic ductal adenocarcinoma (4 papers, 2019 to 2025). An infiltrating adenocarcinoma that arises from the epithelial cells of the pancreas. "This study aims to identify the relevance of XIAP expression as a predictor of overall survival in a large collection of operable pancreatic ductal adenocarcinoma and its correlation with the inflammatory microenvironment." (PMID 36472768, 2023). "In the current study, we analyzed XIAP expression in a cohort of 254 patients with operable pancreatic ductal adenocarcinoma." (PMID 36472768, 2023).
papillary thyroid carcinoma (4 papers, 2017 to 2024). "Clinico-pathologic associations of XIAP expression in papillary thyroid carcinoma." (PMID 36578953, 2022). "X-linked inhibitor of apoptosis (XIAP) is the most potent caspase inhibitory IAP family member and its over-expression is implicated in aggressive behavior of various solid tumors, including papillary thyroid carcinoma (PTC)." (PMID 36578953, 2022). "XIAP expression was significantly higher in the invasive area of ATC samples, whereas XIAP expression was negative in either normal thyroid follicular epithelial cells or the differentiated papillary thyroid carcinoma." (PMID 29221164, 2017).
Parkinson disease (4 papers, 2014 to 2021). A progressive degenerative disorder of the central nervous system characterized by loss of dopamine producing neurons in the substantia nigra and the presence of Lewy bodies in the substantia nigra and locus coeruleus. "K-560 (1a) protected against neuronal cell death in a Parkinson’s disease model by up-regulating the expression of XIAP." (PMID 29362442, 2018). "XIAP overexpression has been demonstrated to prevent neuronal death in models of transient cerebral ischemia and Parkinson's disease." (PMID 25278835, 2014).
prostate tumor (4 papers, 2010 to 2017). "We show here that another endogenous molecule, PN1, can inhibit XIAP, in tissue culture and in vivo, to promote cell death in prostate tumor cells." (PMID 25686839, 2015).